FOXA2 (forkhead box A2)
Diseases named in the same sentence as FOXA2 in open-access papers (continued):
Sharing a sentence is not in itself a finding about the gene and the disease.
breast carcinoma (35 papers, 2012 to 2026). "Downregulation of nuclear FOXA2 is linked to breast cancer metastasis via the AKT pathway." (PMID 41013561, 2025). "In addition to inhibiting downstream EMT-associated transcriptional programs, FOXA2 can be regulated by upstream genes to affect its expression in breast cancer, thereby affecting EMT." (PMID 38605023, 2024). "However, FOXA2 mRNA has also been reported to be associated with relapse in basal-like breast carcinoma." (PMID 36289750, 2022). "Here, the contradictory role of FOXA2 in breast cancer may be associated with the localization of FOXA2." (PMID 36289750, 2022). "Experimental results have revealed that a combination of PGC-1β downregulation and FOXA2 overexpression notably restrained the activity of breast cancer cells through the regulation of the PI3K-AKT-mTOR pathway." (PMID 40003882, 2025). "The results of this study are in complete contrast to previous conclusions that FOXA2 prevents EMT in breast cancer." (PMID 38605023, 2024). "FOXA1 or FOXA2 triggers lipid metabolism reprogramming by maintaining high expression of endothelial lipase (LIPG) in breast cancer, allowing breast cancer cells to grow and extracellular lipids required for proliferation." (PMID 38605023, 2024). "Here, we focus on the role of FOXA1/FOXA2 in cancers affected by steroid hormones, such as PCa, breast cancer, and liver cancer." (PMID 38605023, 2024). "For example, miR-1290 upregulates ciliary neurotrophic factor (CNTF) expression by decreasing FOXA2 expression in astrocytes, promoting breast cancer cell growth and brain metastasis progression." (PMID 38605023, 2024). "In breast cancer, FOXA2 expression prevents breast cancer EMT, and the mechanisms regarding its inhibition are multifaceted." (PMID 38605023, 2024). "High expression of FOXA2 has been shown in neuroendocrine lung cancer and triple-negative/basal-like breast carcinoma." (PMID 38072043, 2023). "In basal-like (or triple-negative) breast cancer cell lines, the in vitro suppression of FOXA2 gene expression decreases proliferation and mammosphere development." (PMID 37626655, 2023). "In light of these encouraging findings, FOXA2 is supported as a peculiar remedial target for the nursing of a particular category of people with triple-negative/basal-like breast cancer who are at an increased danger of recurrent cancer." (PMID 37626655, 2023). "Cdh1 (encoding E-Cadherin) has been reported to be transcriptionally regulated by FOXA2 in gastrulating endoderm as well as oral and breast cancer cells." (PMID 36398878, 2022). "For the first time, we have found that CD44 regulates FOXA2 localization through AKT to promote the metastatic ability of breast cancer cells." (PMID 36289750, 2022). "All these findings suggest that CD44 plays a role in regulating FOXA2 localization in breast cancer cells." (PMID 36289750, 2022). "In another study, FOXA2 has been reported to inhibit mesenchymal transition in breast cancer through E-cadherin and ZEB-1 regulation." (PMID 36289750, 2022). "Collectively, this study highlights that CD44 promotes breast cancer metastasis by downregulating nuclear FOXA2." (PMID 36289750, 2022). "Transcription factor forkhead box protein A2 (FOXA2) acts as an important regulator in multiple cancers, including breast cancer." (PMID 36289750, 2022). "Our current results showed that cytoplasmic FOXA2 expression was higher in basal-type breast cancer cells compared to luminal-type cells." (PMID 36289750, 2022). "We discovered that the mRNA levels of various genes were upregulated in CD44 knockdown cells, and we focused on FOXA2, which has been reported to inhibit epithelial to mesenchymal transition in breast cancer." (PMID 36289750, 2022). "In previous studies, we found that FOXA2 inhibited epithelial-mesenchymal transition (EMT) in breast cancer cells." (PMID 33718155, 2021).
breast carcinoma (continued). "Our previous research found that FOXA2 inhibits EMT in breast cancer cells by stimulating E-cadherin transcription and repressing ZEB2 transcription." (PMID 33718155, 2021). "An in vitro study showed an increased expression of FOXA2 in breast cancer, and that it positively regulated cell proliferation." (PMID 34551777, 2021). "The results confirmed that the FOXP2-improved survival in breast cancer patients was correlated with the high levels of FOXA2." (PMID 33718155, 2021). "The analysis of clinical samples showed that the FOXP2-improved survival in patients depended on the high expression of FOXA2 in breast cancer, implicating involvement of FOXA2 for FOXP2 performing its functions." (PMID 33718155, 2021). "Overall, knockdown of PGC-1β combined with overexpression of FOXA2 apparently inhibited proliferation and migration of breast cancer cells in vitro." (PMID 31007610, 2019). "To explore the biological functions of PGC-1β and FOXA2 in breast cancer progression, we examined the effects of both genes on cell proliferation and clonogenicity by CCK-8 and colony formation assays." (PMID 31007610, 2019). "Consistently, previous studies reported that in breast carcinoma and gastric cancer, patients with higher FOXA2 expression had a better prognosis." (PMID 31689237, 2019). "mRNA and protein expression of PGC-1β and FOXA2 in breast cancer tissues and cell lines were determined by qRT-PCR and Western Blotting, respectively." (PMID 31007610, 2019). "Downregulation of PGC-1β combined with overexpression of FOXA2 obviously inhibited the breast cancer cells proliferation, migration and induced apoptosis through regulating the PI3K-AKT-mTOR signaling pathway." (PMID 31007610, 2019). "We demonstrated that downregulation of PGC-1β combined with overexpression of FOXA2 obviously inhibited the function of breast cancer cells through regulating the PI3K-AKT-mTOR pathway." (PMID 31007610, 2019). "The results showed PGC-1β cooperating with FOXA2 exerted their biological functions in breast cancer through regulating the PI3K-AKT-mTOR pathway." (PMID 31007610, 2019). "As expected, we found PGC-1β and FOXA2 colocalized in the nucleus, and PGC-1β interference combined with FOXA2 overexpression significantly inhibited the proliferation and migration of breast cancer cells." (PMID 31007610, 2019). "To investigate the molecular mechanisms of PGC-1β and FOXA2 in breast cancer progression, we detected the expression of related proteins of PI3K-AKT-mTOR pathway." (PMID 31007610, 2019). "In the present study, we aimed to elucidate the role of PGC-1β and FOXA2 in breast cancer progression." (PMID 31007610, 2019). "In conclusion, our study proved that PGC-1β was high expression while FOXA2 was low expression in breast cancer tissues and cell lines." (PMID 31007610, 2019). "Our results showed that PGC-1β was upregulated and FOXA2 was downregulated in breast cancer tissues and cell lines." (PMID 31007610, 2019). "Meanwhile, we identified that PGC-1β interacts with FOXA2, and it synergizes with FOXA2 to inhibit the biological functions of breast cancer cells through regulating the PI3K-AKT-mTOR signaling pathway." (PMID 31007610, 2019). "In this study, we detected the proteins expression of PI3K-AKT-mTOR signal pathway after transfected with PGC-1β and/or FOXA2 in breast cancer cells." (PMID 31007610, 2019). "We found that PGC-1β is upregulated and FOXA2 is downregulated in breast cancer tissues and cell lines." (PMID 31007610, 2019). "For this, we collected six ChIP-Seq datasets for FOXA1 and FOXA2 in human A549 lung adenocarcinoma cells, HepG2 hepatocellular carcinoma cells, T47D breast cancer cells, and Caco2 CRC cells." (PMID 29155818, 2017). "This revealed a number of significant hotspots of epigenetic deregulation, centred around important breast cancer genes, including FOXA2, PAX6 and L1CAM, with the two largest modules mapping to the WNT and FGF signalling pathways, respectively." (PMID 26823093, 2016).
breast carcinoma (continued). "MicroRNA, a common upstream regulator of FOXA2, can affect FOXA2 expression in breast cancer." (PMID 38605023, 2024). "Thus, FOXA1 and FOXA2 are critical for lipid synthesis and breakdown in breast cancer, suggesting that FOXA1 and FOXA2 are potential therapeutic targets." (PMID 38605023, 2024). "The ability of FOXP2 to inhibit EMT in breast cancer is dependent on FOXA2." (PMID 38605023, 2024). "Moreover, EVs-miR-1290 promotes the progression of breast cancer brain metastasis through the FOXA2-CNTF signaling axis." (PMID 38495881, 2024). "In addition, PGC-1β knockdown and FOXA2 overexpression in breast cancer significantly increased cell proliferation and migration as well as tumor growth." (PMID 38605023, 2024). "Interestingly, the FOXA2 pathway is known to play a role in both breast cancer pathogenesis and lipid metabolism (pleiotropic effect)." (PMID 38947022, 2024). "Additionally, the overexpression of FOXA2 combined with the downregulation of PGC-1β has been recently reported to inhibit breast cancer proliferation and migration and induce apoptosis." (PMID 36289750, 2022). "In breast cancer, FOXA2 is known to attenuate EMT by regulating E-cadherin and ZEB2 expression." (PMID 36289750, 2022). "Additionally, it has been found that FOXA2 interacts with other proteins to inhibit the proliferation and migration of breast cancer cells." (PMID 36289750, 2022). "Furthermore, we found that CD44 mediated FOXA2 localization in breast cancer cells through the AKT pathway." (PMID 36289750, 2022). "Moreover, the immunofluorescence assay demonstrated that AKT inhibitor wortmannin and AKT activator SC79 treatment in breast cancer cells impacted FOXA2 localization." (PMID 36289750, 2022). "In addition, FOXA2 has also been shown to be a target gene of MiR-942, which is involved in the proliferation, migration, and invasion of breast cancer cells." (PMID 34322156, 2021). "FOXA-2 is associated with cell proliferation, invasion, and metastasis of various tumors, and a previous study found that FOXA-2 is overexpressed in triple-negative/basal-like breast cancer cells and is associated with high relapse." (PMID 34681694, 2021). "Together, the results suggested that FOXP2 could inhibit EMT by activating the transcription of certain genes, such as E-cadherin and PHF2, in concert with FOXA2 in breast cancer cells." (PMID 33718155, 2021). "Together, we proposed that FOXP2 could act as a transcriptional activator through its interaction with FOXA2 in breast cancer cells." (PMID 33718155, 2021). "Together, our study highlights the PGC-1β and FOXA2 may be potential targets for the development of breast cancer." (PMID 31007610, 2019). "Collectively, these data clearly demonstrated that abnormal expression of PGC-1β and FOXA2 were frequent event in breast cancer, and they might play vital roles in the development and progression of breast cancer." (PMID 31007610, 2019). "Previous studies have shown that FOXA2 is a critical regulator of embryonic development, and plays a key role in the pathogenesis and occurrence of various cancers, such as prostate cancer, liver cancer, pancreatic cancer, and breast cancer." (PMID 31007610, 2019). "Elevated levels of PGC-1β and low levels of FOXA2 were observed in breast cancer tissues." (PMID 31007610, 2019). "The Foxa2, Msx2, and Zeb2 transcription factors are known to play a role in the epithelial-to-mesenchymal transition and Reln is known to be epigenetically regulated and correlates with prognostic factors in human breast cancer." (PMID 27711132, 2016). "Hurtado and colleagues have reported that FOXA1 is necessary for estrogen to regulate expression of numerous genes in breast cancer cells, and we have just shown that Foxa1 and Foxa2 cooperate in mediating the effects of estrogens and androgens on liver cancer risk in response to carcinogens." (PMID 22737085, 2012). "Co-IP assay indicated that endogenous PGC-1β protein might target to FOXA2 in breast cancer." (PMID 31007610, 2019).
breast carcinoma (continued). "In addition, FOXA2 could maintain breast cancer stem cells, and downregulating it in these cells reduced the formation of spheres and the expression of CD44, ALDH1." (PMID 29187221, 2017). "When the E-cadherin protein is activated, FOXA2 draws the transcriptional corepressor TLE3 to the promoter of ZEB2 to suppress its expression, which can effectively hinder the EMT of breast cancer cells." (PMID 40003882, 2025). "FOXA2, which is highly similar to FOXA1 in the DNA-binding domain (DBD), is also considered to play an important role in the regulation of breast cancer." (PMID 40003882, 2025). "For example, FOXA1, FOXA2, FOXC1, and FOXO3 can all interact with the PI3K/AKT/mTOR pathway and eventually regulate breast cancer cell proliferation." (PMID 40003882, 2025). "Studies have shown that peroxisome gamma coactivator-1β (PGC-1β) is negatively correlated with FOXA2 expression in breast cancer, but PGC-1β binds to FOXA2 to decrease FOXA2 expression in breast cancer and induces EMT." (PMID 38605023, 2024). "CLDN6 expression in breast cancer is regulated by transcription factors such as HIF-1a, FoxA2, Gata6, and TTF-1 at the claudin 6 promoter." (PMID 37762277, 2023). "Another study found that TLE3, a transcription corepressor recruited by FOXA2 to the ZEB2 promoter, inhibits the expression of the EMT-related transcription factor ZEB2, thereby suppressing the EMT of breast cancer cells." (PMID 36451774, 2022). "On the other hand, epithelial breast cancer cells MCF7 and ZR75 showed high FOXA2 expression in the nucleus." (PMID 36289750, 2022). "Taken together, these results suggest that CD44 regulates FOXA2 localization through AKT and promotes metastasis in breast cancer cells." (PMID 36289750, 2022). "Using subcellular fractionation in three breast cancer cell lines, MDA-MB-231, MCF7, and ZR75, we found that, in mesenchymal breast cancer cell line MDA-MB-231, the cytosolic expression of FOXA2 was higher compared to the nucleus." (PMID 36289750, 2022). "Following Western blotting, we confirmed that FOXA2 and FOXP2 interacted physically in breast cancer MCF-7 cells." (PMID 33718155, 2021). "After confirming the interaction between FOXP2 and FOXA2 through Co-IP and immunofluorescence assays, we showed a correlated expression of FOXP2 and FOXA2 existing in clinical breast cancer samples." (PMID 33718155, 2021). "Together, this study confirmed that in concert with FOXA2, FOXP2 acted as a tumor-suppressor through inhibiting EMT of breast cancer cells." (PMID 33718155, 2021). "In the current study, we identified that FOXP2 interacted with FOXA2, and the expression of FOXP2 was strongly correlated with the epithelial phenotype of breast cancer cells." (PMID 33718155, 2021). "We identified networks regulated by known cancer drivers such as GATA3 and FOXA1 (breast cancer), SOX17 and FOXA2 (endometrial cancer), and NFE2L2, SOX2, and TP63 (squamous cell lung cancer)." (PMID 25994056, 2015). "FOXA2 recruits the transcriptional repressor TLE3 to the ZEB2 promoter and inhibits the expression of the EMT-related transcription factor ZEB2, thus preventing EMT in breast cancer cells." (PMID 38605023, 2024). "Based on this data set, we observed a weak correlation between the expressions of FOXA2 and FOXP2 in the samples (R=0.14, p=0.007), while a moderate correlation between their expressions was further found in the subgroup of basal breast cancer especially (n=98, R=0.34, p=0.001)." (PMID 33718155, 2021). "However, the TFs such as KLF5 (52%), KLF1 (39%), and SMAD2::SMAD3::SMAD4 (31%) showed significant enrichment (q < 0.1) in gained peaks and FOX family of TFs (FOXA1 28%, FOXA2 28% and FOXF2 17%) in lost peaks in breast carcinomas." (PMID 34090364, 2021). "In our previous studies, transcription factor FOXA2 was confirmed to inhibit EMT in breast cancer cells by regulating the transcription of EMT-related genes and the stable overexpression of FOXA2 abolished breast cancer cell metastasis in vivo." (PMID 33718155, 2021).
breast carcinoma (continued). "The future analysis of RNA-seq and ChIP-seq of the two factors compared in different subtype cells of breast cancer would provide a foundation to describe the detailed picture of FOXP2 and FOXA2 on regulating EMT progression and metastasis of breast cancer cells." (PMID 33718155, 2021). "Here, we show FOXA1 expression in breast cancer metastases, but it is still unclear whether other FOXA family members such as FOXA2 and FOXA3 also play a role in breast cancer." (PMID 30819139, 2019). "However, in breast cancer, no studies have shown the relationship between FOXA2 and ER, and whether there is a link between the two studies must be further explored in the future." (PMID 38605023, 2024).